ODC1 (ornithine decarboxylase 1)
Diseases named in the same sentence as ODC1 in open-access papers (continued):
Sharing a sentence is not in itself a finding about the gene and the disease.
colorectal cancer (13 papers, 2015 to 2025). A primary or metastatic malignant neoplasm that affects the colon or rectum. "Colorectal cancer (CRC) is associated with mutations in APC/Wnt leading to c-myc activation and the overexpression of ODC1, the limiting step in polyamine synthesis." (PMID 36900391, 2023). "There is evidence that limiting the meat consumption and inhibiting ODC activity can significantly reduce polyamine synthesis and incidence rate of colorectal cancer with ODC1 GA/AA genotype, compared to GG." (PMID 34095122, 2021). "The expression of ODC1 in colorectal cancer was significantly higher than that in the normal colon tissues." (PMID 33915902, 2021). "Our results thus provide added evidence to support the involvement of ODC1 gene in colorectal cancer progression." (PMID 31417867, 2019). "ODC1 protein has been used as a biomarker for measuring the efficacy of colecoxib in the treatment of colorectal cancer." (PMID 31417867, 2019). "In colorectal cancer, studies found that c-MYC had the greatest stimulatory effect on promoters containing the A allele, and interestingly MAD1 was only effective at repressing ODC1 promoter activity in promoters containing the A allele." (PMID 33918978, 2021). "Since there are surprisingly few studies looking at ODC1 expression in adult cancers, we examined a publicly available database and showed that low ODC1 mRNA expression was prognostic of poor relapse-free survival in colorectal cancer." (PMID 33918978, 2021). "Other genes including ODC1 were found to affect colorectal cancer but no causal relationship has been reported so far." (PMID 31417867, 2019). "In colorectal cancer, a more complex network has been identified, where miR-378a was found to inhibit ODC1 both directly by binding to its 3′UTR and indirectly by inhibiting a transcription factor that activates ODC1 transcription." (PMID 38918813, 2024). "The results of coexpression analysis coupled to ENCODE ChIP-Seq data strongly suggest c-Myc and C/EBPβ as regulators of the expression of key enzymes of polyamine metabolism that are upregulated in colorectal cancer: SMOX, AZIN1, MTAP, SRM, AMD1, ODC1, and AGMAT." (PMID 27433286, 2016).
hepatocellular carcinoma (9 papers, 2018 to 2024). A malignant tumor that arises from hepatocytes. "Ornithine decarboxylase 1 (ODC1) is a metabolic enzyme key involved in polyamine biosynthesis, typically upregulated in hepatocellular carcinoma." (PMID 37251321, 2023). "To confirm the critical role of ODC1 in regulating HBV replication in hepatoma cells, we used DFMO, a specific inhibitor against ODC1." (PMID 32373551, 2020). "Choi Y’s research mentioned the up-regulation of the ODC1 in hepatocellular carcinoma and inhibiting the ODC1 can decrease the growth and increase the apoptosis." (PMID 31798625, 2019). "Previous research has shown that ODC1 promotes hepatocellular carcinoma (HCC) proliferation by affecting the AKT/GSK3β/β-catenin pathway." (PMID 36676934, 2022). "Survival in hepatocellular carcinoma (HCC) patients is related to the expression patterns of some genes, including ODC1 (ornithine decarboxylase 1)." (PMID 29966227, 2018).
colitis (8 papers, 2019 to 2025). Inflammation of the colon. "Recent studies have indicated that ODC1 can increase promote colitis and colitis related cancer by inhibiting stimulate epithelial repair, antimicrobial defense, and antitumoral immunity." (PMID 37308808, 2023). "However, ODC1 blockage can significantly reduce the production of inflammatory factors and improve the severity of colitis in mice." (PMID 37308808, 2023). "Moreover, it was found that macrophage ODC1 promotes colitis and colitis-related colon carcinogenesis." (PMID 37308808, 2023). "Reduced Odc1 expression was confirmed by real-time PCR and western blot analysis in WT and AhR-/- BMDMs, as well as in colon tissues in the context of DSS-induced colitis." (PMID 39113799, 2024).
glioma (7 papers, 2020 to 2024). A benign or malignant brain and spinal cord tumor that arises from glial cells (astrocytes, oligodendrocytes, ependymal cells). "Still, cobalt-induced hypoxia in glioma cells resulted in increased expression of ODC1 preceded by HIF1A upregulation." (PMID 32630408, 2020). "The Cancer Genome Atlas (TCGA) and Genotype-Tissue Expression (GTEx) data on normal brain tissue compared with low-grade glioma showed an increase in ODC1 mRNA expression; there was a robust increase in expression in patients with GBM compared with all other groups." (PMID 39561012, 2024).
lung carcinoma (6 papers, 2017 to 2024). "Thus, either low ODC1 expression or an AG/AA SNP genotype is associated with poor outcome in colorectal and lung cancer." (PMID 33918978, 2021).
melanoma (6 papers, 2018 to 2024). A malignant, usually aggressive tumor composed of atypical, neoplastic melanocytes. "While these results require confirmation in independent studies, ODC1 is downregulated in melanoma, compared with controls as well." (PMID 35163453, 2022). "Thus, ODC1 DNA methylation status, the potential impairment of its activity, and its potential role for cancer initiation and propagation should be investigated in melanoma." (PMID 35163453, 2022). "Here, one focus may be on cfDNA exhibiting melanoma cell-specific differentially methylated signatures relying on single, meaningful CpG-rich gene promoter regions, e.g., RASSF1A, LINE-1, or ODC1." (PMID 35163453, 2022). "Key molecular targets in this process, including ODC1, AMD1, DHPS and c-Myc could serve as effective drug targets addressing specific vulnerabilities in BRAFi resistant melanoma, warranting development of novel breakthrough therapies against therapy resistant melanoma." (PMID 38965534, 2024).
adenoma (4 papers, 2017 to 2023). A neoplasm arising from the epithelium. "ODC1 gene polymorphism has been reported to reduce the risk of adenoma recurrence by suppressing synthesis of colonic mucosal polyamines." (PMID 31417867, 2019). "And the 6 coincident genes significantly enriched in adenoma and carcinoma were DEFA6, SOX9, ID1, L1TD1, CXCL3, and ODC1." (PMID 36944972, 2023). "In C2 goblet cells, during the process from normal colon to adenoma and from adenoma to carcinoma, several continuously highly expressed genes were found, including DEFA6, SOX9, ID1, L1TD1, CXCL3, and ODC1." (PMID 36944972, 2023). "We collected the resected carcinoma tissues from CRC patients and conducted immunohistochemical (IHC) staining analysis to examine the expression of some representative genes including NEK8, CHRM3, ANO7, B3GNT6, NEURL1, ODC1 and KCNMA1 in colon normal tissue, adenoma tissue and carcinoma tissues." (PMID 36944972, 2023). "Targeting ODC1 is currently being tested as a chemoprevention strategy in CRC, which, however, is associated with adenoma-carcinoma transformation and not inflammation-induced carcinogenesis." (PMID 32121248, 2020).
Alzheimer disease (4 papers, 2013 to 2024). A progressive, neurodegenerative disease characterized by loss of function and death of nerve cells in several areas of the brain leading to loss of cognitive function such as memory and language. "This study highlights the dichotomous role of ODC1 as the switch between beneficial and detrimental astrocytic processes in Alzheimer’s disease." (PMID 38216963, 2024). "Recently, it was reported that in astroglia of the brain, ODC1 was involved in the conversion of ornithine to putrescine, which further produced GABA and lead to memory impairment in Alzheimer’s disease (AD)." (PMID 38216963, 2024).
brain tumors (4 papers, 2021 to 2024). "We identified increased mRNA levels of ACLY, ASS1 and ODC1 in medulloblastoma primary tumors compared to other pediatric brain tumors, suggesting an increased reliance in medulloblastoma on polyamines, arginine biosynthesis and the TCA cycle/production of acetyl-CoA." (PMID 35267619, 2022).
cardiac hypertrophy (4 papers, 2006 to 2025). "The remarkable mitochondrial oxidative damage to cardiomyocytes in patients with chronic kidney disease (CKD) causes mtDNA leakage, which activates the cGAS-STING-NFκB pathway and NFκB-transactivated ornithine decarboxylase (ODC1)-putrescine metabolic flux, inducing cardiac hypertrophy." (PMID 37163421, 2023). "For example, the Odc1 inhibitor DFMO successfully blocked cardiac hypertrophy normally associated with clenbuterol, and overexpression of Odc1 in a transgenic model resulted in a significant increase in BA stimulated cardiac hypertrophy relative to non-transgenic mice." (PMID 17181869, 2006).
developmental delay (4 papers, 2020 to 2023). "Ornithine decarboxylase 1 (ODC1 gene) has been linked through gain-of-function variants to a rare disease featuring developmental delay, alopecia, macrocephaly, and structural brain anomalies." (PMID 33806076, 2021). "Odc1, which encodes ornithine decarboxylase, is orthologous to ODC1, which is associated with Bachmann-Bupp syndrome, a rare neurodevelopmental disorder with alopecia, developmental delay, and brain abnormalities." (PMID 37036413, 2023). "The natural history of rapid hair loss shortly after birth appears to be unique to this syndrome and could be a reason for consideration of targeted ODC1 gene analysis when observed in any patient with developmental delay." (PMID 34477286, 2021).
diabetes (4 papers, 2014 to 2023). "And the enzyme ornithine decarboxylase 1 (Odc1, 84% reduction in expression) was noted by Thompson, Blantz, and coworkers to be upregulated in diabetes and potentially contributed to aberrant renal growth and hyperfiltration." (PMID 24827579, 2014).
endometrial cancer (4 papers, 2017 to 2025). Primary or metastatic malignant neoplasm involving the endometrium (mucous membrane that lines the endometrial cavity). "ODC1 expression was associated with worse overall survival and increased recurrence in three endometrial cancer gene expression datasets." (PMID 29240775, 2017). "Increased levels of ODC1 were noted in high grade, late stage, serous histology or copy number high cancers which are all features associated with increased rates of recurrence and death in endometrial cancer." (PMID 29240775, 2017). "Importantly, our finding that recurrent cancers have more ODC1 suggests our DFMO-based chemopreventive approach would have particular merit for those cancers that ultimately cause death in patients with endometrial cancer." (PMID 29240775, 2017). "Here, the authors show that oleic acid, increased in MS, promotes endometrial cancer by supporting the stability of the rate-limiting enzyme in polyamine metabolism ODC1 and polyamine accumulation." (PMID 41402312, 2025). "We further explored the expression of ODC1 in endometrial cancers noting significantly elevated expression in both endometrioid and serous cases the two main histotypes of endometrial cancer." (PMID 29240775, 2017). "Since we here investigate ODC1, a key polyamine regulator in endometrial cancers, we decided to also examine other essential enzymes involved in polyamine metabolism in order to address their significance in the disease." (PMID 29240775, 2017). "Amplification and overexpression of MYCN has not been described for human uterine cancer but was noted along with ODC1 as being amplified in rat endometrial cancer." (PMID 29240775, 2017). "We found ODC1 is widely expressed across different histologic types of endometrial cancer as compared to normal endometrial epithelium." (PMID 29240775, 2017). "We noted ubiquitous expression of ODC1 in our published endometrial cancer gene array data and confirmed this in the cancer genome atlas (TCGA) with highest expression in non-endometrioid, high grade, and copy number high cancers, which have the worst clinical outcomes." (PMID 29240775, 2017). "This study links fatty acids to polyamine buildup, reveals a mechanism for metabolic syndrome-driven endometrial cancer, and points to HOXB9 and ODC1 as potential therapeutic targets." (PMID 41402312, 2025). "In addition, to the detailed description of ODC1 expression across endometrial cancer subtypes and normal endometrial cancers we also noted significant changes in the expression of other key regulators of polyamines in endometrial cancers as compared to normal." (PMID 29240775, 2017). "Here we describe the expression characteristics of ODC1 in endometrial cancers and address the preclinical effects of DFMO on endometrial cancer in vitro and in vivo." (PMID 29240775, 2017). "We used cBioPortal and queried endometrial cancers present in the published TCGA cohort and found that those with copy number amplification or gain and elevated expression of MYC also had elevated ODC1 (p = 0.02) (data not shown)." (PMID 29240775, 2017).
Bachmann-Bupp syndrome (3 papers, 2021 to 2024). "For example, in ODC1 (associated with Bachmann-Bupp syndrome, MIM #165640), all 11 pLoFs in UKB occur before the penultimate exon, whilst ClinVar pathogenic variants all occur in the last or penultimate exons." (PMID 38671509, 2024). "Bachmann‐Bupp syndrome (BABS) is a rare syndrome caused by gain‐of‐function variants in the C‐terminus of ornithine decarboxylase (ODC coded by the ODC1 gene)." (PMID 34477286, 2021).
cervical cancer (3 papers, 2019 to 2024). A primary or metastatic malignant neoplasm involving the cervix. "We proceeded to investigate whether the altered regulation of CCND1 and ODC1 proteins by eIF4E was present in the cervical cancer cells." (PMID 32981220, 2020). "For instance, in HPV-positive cervical cancer cells, transcription factor FOXA1 activates the expression of circODC1, which in turn promotes cancer cell growth by competitively binding to miR-607, thereby relieving the inhibition on ODC1." (PMID 38956466, 2024).
gastric cancer (3 papers, 2020 to 2023). A primary or metastatic malignant neoplasm involving the stomach. "ODC1 gene, which catalyzes the first step of polyamine biosynthesis, also showed elevated expression in gastric cancer tissues (Fig. 3a13, b7)." (PMID 37164975, 2023).
lymphoma (3 papers, 2013 to 2015). A malignant (clonal) proliferation of B- lymphocytes or T- lymphocytes which involves the lymph nodes, bone marrow and/or extranodal sites. "Some MYC transactivation targets (ODC1 and CCNA) were very strongly downregulated only in MYC lymphoma cells, but not in MYC p19ARF−/− or MYC p19ARF shRNA knockdown cells." (PMID 25784651, 2015).
viral infection (3 papers, 2022 to 2023). "RT-qPCR and western blot assays showed that the mRNA and protein levels of OAZ1 and ODC1 were both upregulated during viral infection in insect vectors." (PMID 37676339, 2022). "DFMO, a suicide inhibitor of ODC1, was used to inhibit polyamine biosynthesis during viral infection in insect vectors." (PMID 37676339, 2022). "Taken together, these results suggested that RSMV M competed with ODC1 to bind OAZ1, thereby releasing OAZ1 from its inhibiting the function of ODC1 during viral infection in insect vectors." (PMID 37676339, 2022). "Oah, responsible for the biosynthesis of oxalic acid from oxaloacetate, remains unchanged during virus infection whereas oxalate decarboxylase 1 and 2 (odc1 and odc2) are both down regulated in presence of SlaGemV−1 infection." (PMID 36146699, 2022). "OAZ1 in viruliferous insects is mostly recruited by RSMV M to facilitate viral assembly, which in turn competitively prevents the formation of OAZ1-ODC1 heterodimer and thus increases ODC1 homodimer, thereby promoting polyamine production to benefit viral infection." (PMID 37676339, 2022). "Thus, during viral infection, the ability for OAZ1 to mediate the degradation of ODC1 is significantly inhibited, finally leading to the increase of ODC1 in the polyamine biosynthesis pathway." (PMID 37676339, 2022). "More work and fresh clinical samples are needed to determine the expression of ODC-1, EIF5A, Hyp-EIF5A specifically in Th17, Treg, and TregDys in PLWH to achieve a complete understanding of how ODC-1-polyamine-EIF5A hypusination and the auto-regulatory loop impacts Th cells during viral infections." (PMID 36693889, 2023).
atherosclerosis (2 papers, 2023 to 2025). A disease characterized by the build-up of fatty material and calcium deposition in the arterial wall resulting in partial or complete occlusion of the arterial lumen. "Consistently, ODC1 deficiency impairs continual efferocytosis and resolution of atherosclerosis, while putrescine restrains atherosclerosis." (PMID 39863828, 2025). "Furthermore, nanoparticle-mediated silencing of macrophage ODC1 during atherosclerosis decreases IL-10 expression, lowers efferocytosis, and worsens necrotic core area and fibrous cap thickness." (PMID 36710920, 2023). "Mice lacking myeloid Arg1 or ODC1 have selective defects in continual efferocytosis and prevent atherosclerosis regression." (PMID 36710920, 2023).
Cerebral ischemia (2 papers, 2020 to 2023). Restriction of arterial blood supply to the brain associated with insufficient oxygenation to support the metabolic requirements of the tissue. "Consistent with our results, odc1 mRNA expression is upregulated after cerebral ischemia in gerbils, and its enzymatic activity is increased after spinal cord injury, mechanical brain injury and cerebral ischemia in rats." (PMID 32366533, 2020).
colorectal adenoma (2 papers, 2012 to 2018). An adenoma that arises from the colon or rectum. "Interestingly, SNP rs11694911, which is located downstream to the ODC1 gene has previously been shown to be associated with increased risk of colorectal adenoma." (PMID 29425227, 2018). "However, targeting of ODC1 has been successfully used in a combination therapy trial where a low dose of chemopreventive drugs difluoromethylornithine (DFMO; targeting ODC1) plus sulindac has shown notable efficacy in preventing colorectal adenoma recurrence with few side effects." (PMID 22280838, 2012).
epilepsy (2 papers, 2013 to 2021). A brain disorder characterized by episodes of abnormally increased neuronal discharge resulting in transient episodes of sensory or motor neurological dysfunction, or psychic dysfunction. "ODC1 has been linked to additional diseases like cancer, with growing evidence for neurological contributions to schizophrenia, mood disorders, anxiety, epilepsy, learning, and suicidal behavior." (PMID 33806076, 2021).
Hirsutism (2 papers, 2019 to 2022). Abnormally increased hair growth referring to a male pattern of body hair (androgenic hair). "It should be emphasized that an inhibitor (DFMO) of the polyamine biosynthesis enzyme ODC1 has been approved by the US FDA for facial hirsutism treatment, and preclinical data characterized DFMO as a potential tumor prevention reagent." (PMID 35243242, 2022).
ischemia (2 papers, 2013 to 2025). A hypoperfusion of the BLOOD through an organ or tissue caused by a PATHOLOGIC CONSTRICTION or obstruction of its BLOOD VESSELS, or an absence of BLOOD CIRCULATION. "In IS, altered ODC1 activity may similarly influence microglial activation and neuronal survival post-ischemia, positioning it as a key modulator of the shared inflammatory microenvironment in both conditions." (PMID 41305834, 2025).
liver cancer (2 papers, 2024). An epithelial or non-epithelial malignant neoplasm that arises from the liver. "In liver cancer, the expression and activity of ODC1 were elevated compared to normal tissues." (PMID 38395945, 2024).